RN7SKP266 (RN7SK pseudogene 266)
Gene: Miscellaneous RNA gene on chromosome 7 (18,807,993 to 18,808,279, reverse strand). Ensembl gene ENSG00000222164.
Homologues: Orthologues: chimpanzee 7SK (91% identical), guinea pig 7SK (61% identical), mouse Gm55578 (56% identical). Paralogues in human: RN7SKP245 (71% identical), RN7SKP180 (71% identical), RN7SKP203 (71% identical), RN7SKP255 (71% identical), RN7SKP296 (71% identical), RN7SKP217 (70% identical), RN7SKP75 (70% identical), RN7SKP71 (70% identical), RN7SKP145 (70% identical), RN7SKP176 (70% identical), RN7SKP134 (69% identical), RN7SKP144 (69% identical), and 284 more.